SNAP23 (synaptosome associated protein 23)
Description:
SNAREs (soluble N-ethylmaleimide-sensitive factor-attachment protein receptors) are essential proteins for intracellular membrane fusion. SNAREs localized on opposing membranes assemble to form a trans-SNARE complex, an extended, parallel four-helix bundle whose assembly releases energy that drives membrane fusion. The core SNARE complex typically consists of four alpha-helical domains, three from target membrane SNAREs (t-SNAREs) and one from a vesicle SNARE (v-SNARE). SNAP23 is a t-SNARE (target-SNARE) that resides on target membrane and functions in the fusion of transport vesicles with the plasma membrane in immune cells. In macrophages, regulates the stimulus-dependent vesicular transport of TLR4 from recycling endosomes to the plasma membrane by cooperating with STX11 and thereby plays a critical role in the recognition of microbial components and the induction of innate and adaptive immunity. In skeletal muscle satellite cells, SNAP23 cooperates with its cognate SNAREs VAMP4 and STX11 to facilitate CD36 vesicular transport from endosomes to the plasma membrane, an essential step in muscle regeneration (By similarity).
Synonyms: SNAP-23; SNAP23A; SNAP23B; HsT17016
Tractability: Antibody: its Gene Ontology location is reachable by antibodies, with high confidence; UniProt places it where antibodies can reach, with medium confidence; the Human Protein Atlas places it where antibodies can reach. PROTAC: ubiquitination databases record sites on it; its protein half-life has been measured.
Gene: Protein-coding gene on chromosome 15 (42,491,233 to 42,545,356, forward strand). Ensembl gene ENSG00000092531.
Subcellular location: Cell membrane
Subcellular location (Human Protein Atlas): Plasma membrane; Primary cilium
Pathways (Reactome):
Signal Transduction: CDC42 GTPase cycle; RAC1 GTPase cycle; RAC3 GTPase cycle; RHOA GTPase cycle; RHOB GTPase cycle; RHOF GTPase cycle; RHOJ GTPase cycle; RHOQ GTPase cycle
Immune System: ER-Phagosome pathway; Neutrophil degranulation
Vesicle-mediated transport: Translocation of SLC2A4 (GLUT4) to the plasma membrane; trans-Golgi Network Vesicle Budding
Gene Ontology:
Molecular function: fusogenic activity; protein binding; SNAP receptor activity; syntaxin binding
Biological process: cytotoxic T cell degranulation; endosome to plasma membrane protein transport; histamine secretion by mast cell; vesicle fusion; exocytosis; synaptic vesicle fusion to presynaptic active zone membrane; synaptic vesicle priming
Cellular component: adherens junction; azurophil granule; cytoplasm; extracellular exosome; focal adhesion; immunological synapse; mitochondrion; plasma membrane; SNARE complex; specific granule; phagocytic vesicle membrane; specific granule membrane; tertiary granule membrane; cytoplasmic side of membrane; cytoplasmic vesicle; presynapse
Genetic constraint (gnomAD): Loss-of-function variants: 7 observed, 16.33 expected, observed/expected ratio (o/e) 0.43, 90% interval 0.24 to 0.81. The upper end of that interval is the gene's LOEUF score, 0.81, which puts it in group 3 of 6, group 1 being the genes least tolerant of losing a copy. Missense variants: 118 observed, 150.82 expected, observed/expected ratio (o/e) 0.78, 90% interval 0.67 to 0.91. Synonymous variants: 35 observed, 49.83 expected, observed/expected ratio (o/e) 0.7, 90% interval 0.54 to 0.93.
Homologues: Orthologues: chimpanzee SNAP23 (100% identical), rabbit SNAP23 (90% identical), macaque SNAP23 (89% identical), dog SNAP23 (89% identical), pig SNAP23 (88% identical), mouse Snap23 (87% identical), rat Snap23 (87% identical), guinea pig SNAP23 (82% identical), tropical clawed frog snap23 (69% identical), zebrafish snap23.1 (62% identical), zebrafish snap23.2 (36% identical). Paralogues in human: SNAP25 (59% identical), SNAP47 (23% identical), SNAP29 (22% identical).
Diseases named in the same sentence as SNAP23 in open-access papers:
SNAP23 is named in the same sentence as 58 diseases in open-access papers, as found by Europe PMC text mining. Sharing a sentence is not in itself a finding about the gene and the disease. The quoted sentences say what the papers report.
breast carcinoma (7 papers, 2013 to 2026). "Our data shows that the proteins with the highest fold change in breast cancer were carbonic anhydrase 13 (CA13), sulfatase-modifying factor 2 (SUMF2), and synaptosomal-associated protein 23 (SNAP23)." (PMID 37064098, 2023). "OLR1, GLRX and SNAP23 were overexpressed in human prostate and breast cancer tissues and high expression levels of these molecules are associated with aggressive phenotype and metastatic stage." (PMID 23292678, 2013). "Among those, neutral sphingomyelinase 2 (nSMase2), phosphorylated synaptosome-associated protein 23 (SNAP23) and Ras-related RAB proteins (RAB27A/RAB27B) regulate sEV secretion from different cancer cells like breast cancer, hepatocellular carcinoma (HCC), and colorectal cancer." (PMID 32225076, 2020). "In this study, we identified syntaxin‐4, SNAP‐23, and VAMP‐7 as the SNAREs responsible for exosome secretion in MCF‐7 breast cancer cells and found that a SNARE complex consisting of these SNAREs can drive membrane fusion in vitro." (PMID 37700095, 2023). "For example, GLRX, SNAP23 and OLR1 are overexpressed, which is related to aggressive metastasis in breast cancer and prostate cancer tissues." (PMID 38017548, 2023). "In this study, we identified syntaxin‐4, SNAP‐23, and VAMP‐7 as the cognate SNAREs that mediate exosome secretion in MCF‐7 human breast cancer cells." (PMID 37700095, 2023).
diabetes (7 papers, 2015 to 2025). "The present study unravels further mechanistic evidence regarding the formation of SNARE complexes and suggests a potential role for SNAP23 in the pathogenesis of diabetes mellitus." (PMID 37057886, 2023). "The role of SNAP23 Ser-95 requires further investigations in diabetes mellitus and other human diseases because numerous kinases, such as PKC, are activated under pathological and physiological conditions." (PMID 37057886, 2023). "Interestingly, an increase in IBD/IBS was also observed for CA13 (carbonic anhydrase XIII), protein associated with colorectal cancer (CRC), as well as SNAP23 (synaptosomal-associated protein 23) and NADK (NAD kinase) which are linked to insulin signalling and type 2 diabetes mellitus (T2DM)." (PMID 40481885, 2025). "Therefore, SNAP23 can be a potential therapeutic target in diabetes." (PMID 37057886, 2023). "Therefore, SNAP23 may be a potential therapeutic target for diabetes mellitus." (PMID 37057886, 2023).
colorectal cancer (6 papers, 2019 to 2025). A primary or metastatic malignant neoplasm that affects the colon or rectum. "The unique regulatory function of SNAP23 in the chemotherapeutic response of colorectal cancer may provide a potential target for chemotherapy sensitization." (PMID 41274938, 2025).
Insulin resistance (6 papers, 2016 to 2024). Increased resistance towards insulin, that is, diminished effectiveness of insulin in reducing blood glucose levels. "A new mouse model of adipocyte-specific SNAP23 knockout showed peripheral insulin resistance, supporting the concept that SNAP23 is physiologically important for glucose uptake into adipocytes in vivo." (PMID 35774142, 2022). "Thus, it is suggested that GLUT4 translocation with SNAP23 redistribution plays a role in insulin resistance in skeletal muscle in patients with PCOS." (PMID 38674428, 2024). "Taken together, our results revealed SLN-RES could be a modern and interestingly therapeutic approach for the improvement of insulin resistance through targeting the expression of Snap23, Stx4, and Vamp2 in adipose and muscle tissues." (PMID 31290033, 2019).
melanoma (6 papers, 2016 to 2024). A malignant, usually aggressive tumor composed of atypical, neoplastic melanocytes. "This treatment resulted in the reduction of SNAP-23 expression in melanoma cells of 60–70%, as detected by polymerase chain reaction and by antibody staining." (PMID 26940455, 2016). "Curiously, melanoma patients present a higher expression of SNAP23 and LC3 after MAPK inhibitors treatment, although the clinical significance of this finding remains unknown." (PMID 35008395, 2022). "Accordingly, when we monitored the exposure of LLE vesicles (as detected by the addition of Av-SRho to the culture medium) on the surface of melanoma cells with reduced SNAP-23 expression, a profound inhibition of endosomal vesicle exocytosis was observed, as detected by a lower Av-SRho uptake." (PMID 26940455, 2016). "We next investigated the impact of SNAP-23 silencing on melanoma cell resistance to CTL attack." (PMID 26940455, 2016). "To assess Notch1 and Notch2 activity, we used SNAP23 and BCAT2, two downstream targets of Notch1 and 2, respectively, that we identified by a microarray analysis of human melanoma cells in which each Notch receptor was inhibited by a specific shRNA." (PMID 39491031, 2024). "Only five genes were found to be predictive of good outcome when highly expressed in melanoma: LYSMD2, PSPIP2, SNAP23, TSHR, and CCPG1." (PMID 36553569, 2022). "In addition, syntaxin‐4, SNAP‐23, and VAMP‐7 play equivalent roles in exosome secretion in both HeLa cervical cancer cells and A375 melanoma cells, suggesting their conserved function in exosome secretion." (PMID 37700095, 2023). "We tested whether the reduced SNAP-23 expression would interfere with the dynamics and secretion of LLE compartments in melanoma cells." (PMID 26940455, 2016).
ovarian carcinoma (6 papers, 2016 to 2025). A malignant neoplasm originating from the surface ovarian epithelium. "The Human Protein Atlas immunohistochemistry (IHC) analyses showed that SNAP23 was rarely expressed in normal ovary tissues, while was expressed in most ovarian cancer tissues (9 of 11)." (PMID 27855700, 2016). "We next used KEGG pathway and GO analysis (DAVID Bioinformatics Resources 6.7) on a list of genes co-expressed with SNAP23 that was obtained from cBioportal using both RNA-seq and microarray results of Ovarian Cancer (TCGA, Provisional)." (PMID 27855700, 2016). "Notably, O-GlcNAcylation of SNAP-23 is vital for regulating exosome release in ovarian cancer cells." (PMID 34001861, 2021). "In conclusion, our study identified SNAP23 as a novel oncogene in Ovarian Cancer." (PMID 27855700, 2016). "Indeed, it is reported that inhibition of O-GlcNAclation of SNAP-23 could affect the exosome release by ovarian cancer cells, leads to changes in chemoresistance." (PMID 35795059, 2022). "And our research was to explore whether SNAP23 could influence the ovarian cancer progression." (PMID 27855700, 2016). "In this study, downregulation of OGT-mediated O-GlcNAcylation of SNAP-23 promoted the formation of SNAP-23-Stx4-VAMP8 complex and increased exosomes release in ovarian cancer, which increased cisplatin efflux through exosomes and reduced the intracellular cisplatin concentration." (PMID 37497408, 2023). "For example, downregulation of O-GlcNAclation transferase (OGT) reduces O-GlcNAc modification of SNAP-23, thereby promoting the formation of SNARE complex composed of SNAP-23, VAMP8, and Syntaxin-4 and eventually promoting exosome biogenesis in ovarian cancer cells." (PMID 36320056, 2022). "KM plot analysis suggests that ovarian cancer patients strongly expressing SNAP23 has a poor progression free survival than those with absent or weaker SNAP23 expression." (PMID 27855700, 2016).
hepatocellular carcinoma (5 papers, 2019 to 2025). A malignant tumor that arises from hepatocytes. "It has been reported that lncRNA HOX transcript antisense RNA (HOTAIR) promotes exosome secretion of hepatocellular cancer cells by regulating Ras-Related Protein Rab-35 (Rab35) and Synaptosome Associated Protein 23 (SNAP23)." (PMID 41551597, 2025). "The abnormal lncRNA LINC00511 induces formation of invadopodia by regulating the colocalization of VAMP7 and synaptosome associated protein 23 (SNAP23) and is thus involved in tumor progression as shown in hepatocellular carcinoma (HCC) cells." (PMID 35008434, 2021). "In hepatocellular carcinoma, SNAP23 and VAMP3 are required for the fusion event, which can be regulated by lncRNA HOTAIR." (PMID 36320056, 2022).
Type 2 Diabetes (5 papers, 2013 to 2025). "For example, an up-regulation of STX6 mRNA 2 h post stimulation with LPS has been reported in RAW 264.7 macrophage cells and SNAP23 mRNA from the skeletal muscle of patients with type II diabetes was up-regulated." (PMID 25674084, 2014). "Future research should also investigate whether SNAP23 is hijacked from the plasma membrane in obese individuals and patients with type 2 diabetes." (PMID 26733245, 2016). "Moreover, increased partitioning of SNAP23 to cytosolic/microsomal compartments and reduced SNAP23 expression at the plasma membrane was also observed in studies using muscle cells of type-2 diabetic patients." (PMID 24040030, 2013).
atherosclerosis (4 papers, 2013 to 2024). A disease characterized by the build-up of fatty material and calcium deposition in the arterial wall resulting in partial or complete occlusion of the arterial lumen. "Additionally, we identified 4 new MMVD stage B2 targets (MDM2, ROCK1, RIPK1, and SNAP23) that have been studied in many cardiovascular diseases in human medicine, such as chronic heart failure, atherosclerosis, and diabetic cardiomyopathy." (PMID 38087280, 2023). "Notably the in vivo intervention of VAMP3/SNAP23 by systemic delivery of rapamycin ameliorates thrombi formation, echoing the value of mTOR inhibition in preventing the development of atherosclerosis." (PMID 33224946, 2020). "The five key genes related to three pathways included the SNARE interactions in the vesicular transport pathway (SNAP23, VTI1A), the insulin signaling pathway (IRS2, PRKAR1A), and lipid and atherosclerosis (CASP1)." (PMID 38674428, 2024). "The authors of that study noted that multiple genes involved in lipid metabolism, cholesterol biosynthesis and atherosclerosis, including OLR1 (oxidized LDL receptor 1), SCD1, SREBP1, SNAP23 and VAMP4 were deregulated in cell transformation." (PMID 23292678, 2013).
Sepsis (4 papers, 2020 to 2026). Sepsis is defined as life-threatening organ dysfunction caused by a dysregulated host response to infection. "Lastly, we demonstrated that IKK controlled platelet-derived exosome secretion during sepsis, which was in alignment with previous research showing that IΚΚ controls platelet secretion through regulating SNAP-23 phosphorylation." (PMID 32600436, 2020). "As an example, TAT-SNAP-23 (a fusion protein containing the N-terminal SNAP-23 SNARE domain fused with the cell penetrating HIV peptide TAT) was reported to attenuate lung injury evoked by pulmonary immune complex deposition or sepsis." (PMID 35371088, 2022). "ISE pretreatment diminished enhanced SNAP-23 and VAMP-8 protein expression in the platelets of CLP-induced sepsis mice (n = 5 independent experiments)." (PMID 38921594, 2024).
prostate carcinoma (3 papers, 2016 to 2023). A carcinoma that arises from epithelial cells of the prostate gland. "A recent study found that lipid-related genes such as SNAP23 were important for cell transformation and were significantly elevated in advanced breast and prostate cancers." (PMID 27855700, 2016). "Prostate cancer progression has been linked to high-level expression of lipid metabolism genes (e.g., OLR1, GLRX and SNAP23) which could contribute to the dysregulation of lipid distribution in the tumor cell membrane." (PMID 35631014, 2022).
(HCMV) infection (2 papers, 2016 to 2023). "It has been previously reported that human cytomegalovirus (HCMV) infection induces the relocation of SNAP23 to the cytoplasmic viral assembly zone and knockdown of SNAP23 inhibits viral production." (PMID 27550144, 2016). "HCMV infection causes remodeling of the secretory pathway, in part through viral miRNAs that target members of the endocytic pathway, such as ras-related protein rab-5 (RAB5) and synaptosomal-associated protein 23 (SNAP23), which could influence MVB exocytosis dynamics in infected cells." (PMID 37575190, 2023).
dementia (2 papers, 2023 to 2025). Loss of intellectual abilities interfering with an individual's social and occupational functions. "Synaptic dysfunction is a common hallmark of dementia, involving both specific presynaptic as well as postsynaptic proteins, which are postsynaptic density protein (PSD-95) and synaptosomal-associated protein 23 (SNAP-23)." (PMID 40114925, 2025). "Synaptic loss is a common hallmark of dementia, involving both specific presynaptic as well as postsynaptic proteins, which are postsynaptic density protein (PSD-95), synaptosomal-associated protein 23 (SNAP-23), synaptosomal-associated protein 25 (SNAP-25), and synaptophysin (SYP)." (PMID 38068844, 2023).
fatty liver disease (2 papers, 2016 to 2020). A reversible condition wherein large vacuoles of triglyceride fat accumulate in liver cells via the process of steatosis. "Correspondingly, adipocyte apoptosis caused by adipocyte-specific deletion of the synaptosomal-associated protein 23 (Snap23) gene led to IR and hepatic steatosis." (PMID 33372630, 2020).
head and neck cancer (2 papers, 2023 to 2025). A primary or metastatic malignant neoplasm affecting the head and neck. "In addition, we observed comparable depletion results upon knockdown of SNAP23 in a FANCA-null background versus WT background in Cal33 cells, another head neck cancer cell line." (PMID 41188232, 2025).
pancreatitis (2 papers, 2023 to 2024). Inflammation of the pancreas. "Pancreatitis stimuli motivates SNAP23 connection with the STX17 SNARE complex required for autolysosome formation." (PMID 36793898, 2023). "Knockout of SNAP23 impaired the assembly of STX4‐driven basolateral exocytotic SNARE complex and STX17‐driven SNARE complex, resulting in reduction of autophagosome formation, thus protecting pancreatitis progression." (PMID 39500626, 2024). "SNAP23-KD-induced blockade of autophagosome-lysosome fusion by inhibiting SNARE complex which mediates fusion of these two vesicles in experimental pancreatitis rather than physiological starvation." (PMID 36793898, 2023).
allergic reactions (1 paper, 2011).
autoimmune disease (1 paper, 2017). A disorder resulting from loss of function or tissue destruction of an organ or multiple organs, arising from humoral or cellular immune responses of the individual to their own tissue constituents. "Targeting SNAP23 and other SNAREs responsible for phagosomal maturation might be a novel strategy to combat autoimmune diseases, infection and cancer." (PMID 28202687, 2017).